IL6 (interleukin 6)
Diseases named in the same sentence as IL6 in open-access papers (continued):
Sharing a sentence is not in itself a finding about the gene and the disease.
malaria (continued). "Malaria-infected women had significantly elevated IL-10 levels and a decreased IL-6:IL-10 ratio compared with non-infected women (p = 0.005)." (PMID 41666219, 2026). "First, the associations between inflammatory markers and parasite counts suggest that IL-6 and TNF-α could serve as biomarkers for malaria severity and therapeutic monitoring." (PMID 40061813, 2025). "Similarly, IP-10, MCP-1, IL-6 and IFNγ were negatively correlated (P < 0.05) while TGF-β1 was positively correlated (r = 0.2; P < 0.05) with previous malaria episodes." (PMID 40690473, 2025). "Moreover, regarding headaches in malaria, scholars showed that pro-inflammatory cytokines such as TNF-α and IL-6 have an important role in the pathogenesis of headaches in malaria." (PMID 40333915, 2025). "In malaria patients with HbS, serum levels of C-X-C motif chemokine ligand 10 (CXCL10), tumor necrosis factor-α (TNF-α), chemokine (C-C motif) ligand 2 (CCL2), interleukin-8 (IL-8), and interleukin-6 (IL-6) are lower compare to malaria patients without HbS." (PMID 40993672, 2025). "While cytokines such as IL-6, IL-1β, and TNF-α have been extensively studied in relation to malaria severity, the role of IL-2 in immune regulation, T cell activation, and its potential dual contributions to both protective and pathogenic responses remain less well understood." (PMID 41194029, 2025). "Therefore, the present study indicates the potential impact of I. oblongifolia as an effective therapy for malaria disease, focusing on the microscopic analysis and immunobiological alterations particularly the levels of TNF-α and IL-6." (PMID 40917784, 2025). "Malaria‐infected children had higher tumor necrosis factor alpha (TNF‐α) (p < .001), interferon‐gamma (IFN‐ɣ) (p < .001), interleukin (IL)‐1β (p < .001), IL‐6 (p < .001), granulocyte macrophage‐colony stimulating factor (GM‐CSF) (p < .001), and IL‐10 (p < .001) levels than controls." (PMID 39240033, 2024). "The inflammatory condition of malaria is characterized by free radical generation and excessive release of pro-inflammatory cytokines such as tumor necrosis factor (TNF)-alpha, interleukin (IL)-12, IL-10, IL-6, and interferon (IFN)-gamma." (PMID 36852070, 2023). "Increased TNF, IFN-γ, IL-1, IL-2, IL-6, IL-10, TGF-β, CCL2, CCL3, and G-CSF levels and decreased IL-5, IL-12, IL-17, and CCL11 levels were observed in malaria monoinfection compared to intestinal parasite monoinfection." (PMID 36716305, 2023). "This evidence does not support the consideration of IL-6 manipulation in patients with severe malaria." (PMID 36801374, 2023). "In MR analyses using rs2228145, we did not identify an effect of decreased IL-6 signaling on severe malaria (odds ratio 1.14, 95% confidence interval 0.56-2.34, P = 0.713)." (PMID 36801374, 2023). "Across all populations, we saw little evidence of any effect of IL-6 signaling on severe malaria, with all estimates crossing the null but with a large degree of imprecision reflected by wide confidence intervals (CIs) across all estimates." (PMID 36801374, 2023). "Increased IL-6 and IL-10 levels were observed in cerebral malaria compared with severe malaria without a cerebral involvement." (PMID 36668942, 2023). "An analysis of the cord blood revealed that TNF, IL-1β, and IL-5 were associated with severe malaria but IL-4, IL-6, IFN-γ, and IL-10 did not relate to severe malaria." (PMID 36668942, 2023). "Cases of malaria and dengue coinfection also exhibited the highest values of IFN-γ and IL-6." (PMID 36716305, 2023). "Taken together, the results of our meta-analysis showed that IL-6 levels were not different in patients with uncomplicated malaria and asymptomatic malaria." (PMID 35396564, 2022). "Subgroup analysis of IL-6 measurement with an ELISA showed higher mean IL-6 levels in patients with severe malaria than in those with non-severe malaria." (PMID 35396564, 2022).
malaria (continued). "Subgroup analysis of malarial complications showed higher mean IL-6 levels in patients with cerebral malaria than in those with non-severe malaria (P = 0.002, WMD = 70.44 pg/mL, 95% CI = 25.76–115.13 pg/mL, I2 = 99.7%, three studies)." (PMID 35396564, 2022). "STHs would be protective against malaria according to the IL-10/TNF-α ratio, while according to the IL-10/IL-6 ratio, intestinal protozoa may have a detrimental effect." (PMID 35421083, 2022). "Publication bias was assessed with two analyses: differences in IL-6 levels between severe and non-severe malaria cases, and differences in IL-6 levels between uncomplicated malaria and controls." (PMID 35396564, 2022). "For the analysis of differences in IL-6 levels between severe and non-severe malaria, a funnel plot demonstrated the asymmetrical distribution of effect estimates, which were far from the middle line of the plot." (PMID 35396564, 2022). "Differences in IL-6 levels between patients with severe and non-severe malaria cases were estimated using the available data of 13 studies." (PMID 35396564, 2022). "The result from that study was confirmed by a subgroup analysis that showed higher mean IL-6 levels in patients with cerebral malaria compared to those with non-severe malaria." (PMID 35396564, 2022). "In Africa, the highest difference in IL-6 levels was found in a study conducted in Mali7 and all studies included in the meta-analysis reported higher mean IL-6 levels in patients with malaria than patients with non-severe malaria." (PMID 35396564, 2022). "Results showed a higher level of sTREM-1 and IL-6 in individuals with malaria compared with individuals without the infection (P < 0.05)." (PMID 35749690, 2022). "In conclusion, significantly increased levels of IL-6 were observed in patients with severe malaria compared with those in patients with non-severe malaria, which indicates that IL-6 is a candidate marker for severe malaria." (PMID 35396564, 2022). "The results showed that patients with severe malaria had higher mean IL-6 levels than those with non-severe malaria (P = 0.04, WMD = 96.63 pg/mL, 95% CI = 4.322 − 188.89 pg/mL, I2 = 99.9%, 13 studies)." (PMID 35396564, 2022). "Subgroup analysis of age groups showed higher mean IL-6 levels in those with severe malaria than in those with non-severe malaria among studies that enrolled patients of all age groups." (PMID 35396564, 2022). "Other previous research focused on clinical malaria, demonstrating that circulating blood samples of clinical malaria patients produced a lower cytokine response and contained less TNF-α and IL-6 producing monocytes compared to healthy controls upon stimulation with E. coli LPS." (PMID 34177883, 2021). "Elevated levels of IL-4 and IL-10 and reduced levels of IL-6 were detected in the malaria positive samples in comparison to the negative ones in the three types of the samples investigated." (PMID 33422078, 2021). "However, in these experiments M2 macrophages increased production of the pyrogenic cytokines IL-1β, IL-6 and TNF, and malaria-specific opsonising antibodies have been directly shown to promote inflammation in human macrophages." (PMID 33752799, 2021). "The mean serum IL-6 levels of children without malaria, with mild, moderate and severe malaria was 30.3 ± 8.7 pg/mL, 83.7 ± 13.5 pg/mL, 98.5 ± 15 pg/mL and 101 ± 18.4 pg/mL, respectively." (PMID 35223394, 2021). "In malaria volunteer infection studies, despite the low parasite counts, participants still experience a significant inflammatory response, with elevated levels of IFN-γ and IL-6 potentially contributing to inhibition of erythropoiesis." (PMID 34930260, 2021). "Similar to responses seen with DCs from malaria-naïve US donors, mDCs obtained from Malians did not secrete significant amounts of the inflammatory cytokines IL-1β, IL-6 or TNF." (PMID 33407502, 2021).
malaria (continued). "The lack of IL-6 only modestly affected Tfh cells by reducing the levels of ICOS expression in both malaria models." (PMID 36845571, 2021). "The significant increases in IL-6 and TNF-α level observed in the HIV seropositive pregnant participants with malaria coinfection could be indicative of viral replication." (PMID 33193759, 2020). "On the other hand, the IL-6 level was significantly lower in HIV seropositive pregnant women without (1.83 ± 0.55) and HIV seronegative pregnant women with malaria (1.80 ± 0.57) compared with HIV seronegative pregnant women without malaria parasitemia (2.34 ± 0.90) (p=0.023, 0.016, respectively)." (PMID 33193759, 2020). "Pro-inflammatory chemokines (CXCL10, CCL2, and CCL3) and cytokines (TNF-α, IL-8, and IL-6) were reported to mediate severe malaria and SCD separately but have not been examined in SCD individuals infected with malaria." (PMID 33424841, 2020). "It was also determined that malaria outcomes could be altered based on the crosstalk between inflammatory cytokines (CXCL10, CCL3, IL-8, TNF-α, and IL-6) and Hb genotypes." (PMID 33424841, 2020). "Hence, the clinical features of malaria are due to release of pro-inflammatory cytokines including TNF, interferon-gamma, IL-6, and IL-12." (PMID 33357220, 2020). "A significantly higher level of IFN-γ, TNF-α, IL-6, and IL-10 were expressed by co-infected cases than malaria cases, except for TGF-β which did not vary significantly." (PMID 31687034, 2019). "Thus, the levels of both tissue and plasma IFNγ, TNFα, and IL-6 were assessed in WT and TRPV1KO mice with malaria." (PMID 31223430, 2019). "Similarly, the Malaria+CHB group had significantly elevated pro-inflammatory cytokines, including tumour necrosis factor alpha (TNF-α), interleukin (IL)-1β, and IL-6 [P<0." (PMID 31002731, 2019). "In the context of malaria, altered placental cytokine concentrations have been demonstrated in the presence of infection, with increased expression of both pro-inflammatory cytokine (IL-1β and TNF) and chemokines (CXCL8), and decreased expression of IL-6." (PMID 31188820, 2019). "Serum levels of IL1-β, IL-6, CXCL1 and MCP-1 were evaluated to determine whether gestational malaria induced a systemic inflammatory response." (PMID 31391498, 2019). "It has been reported that imbalance of cytokines such as tumor necrosis factor alpha (TNF-α), interleukin-6 (IL-6), IL-10 and interferon gamma (IFN-γ) resulting from malaria related-inflammation can induce changes in iron absorption and distribution (iron delocalization)." (PMID 31760954, 2019). "Additionally, malaria pathogenicity genes (thrombospondin 1-(THBS 1), interleukin 6 (IL6), and arginine decarboxylase 2 (ADC2)) were down-regulated." (PMID 31792230, 2019). "In severe malaria in Malawian children, the inflammatory monocyte subset was expanded and activated with higher plasma levels of inflammatory cytokines (IFNα, IFNγ, TNF-α, IL-6) and chemokines (CCL2, CCL3, CCL4, CXCL10) than in convalescence." (PMID 30581439, 2018). "Indeed, only in the younger age group were TNF, IL6, and IL2 concentrations elevated during acute malaria (day 0) as compared to convalescence (week 3)." (PMID 29284469, 2017). "Regarding IL-6, its level in peripheral, placental and cord plasma was slightly higher in women with chronic infection than in those with infection or with neither malaria parasite nor pigment in the placenta." (PMID 27871325, 2016). "Moreover, amongst the clinical groups assessed herein, cases of malaria and dengue co-infection also exhibited the highest values of IFN-γ and IL-6." (PMID 26271921, 2015). "In experimental murine malaria, it has been shown that IL-6 trans-signaling, rather than classic IL-6 signaling, contributes to malaria-induced lethality." (PMID 25408684, 2014).
malaria (continued). "Since none of our patients presented severe or complicated malaria, the higher serum levels of IL-6 and IL-10 seem to suggest an attempt of IL-6 to induce mechanisms that control the parasite and IL-10, in its turn, to control the inflammation." (PMID 24741587, 2014). "Support for this modulatory hypothesis comes from the description that IL-10 and IL-4 can directly down regulate pro-inflammatory cytokines such as IL-6, TNF and IL-1β and prevent severe forms of malaria." (PMID 23433077, 2013). "IL-6 levels were also higher in travelers (13.085 [8.17; 27.69] pg/mL) and immigrants (10.59 [5.65; 43.1] pg/mL) with malaria than in patients without malaria (5.26 [0.6; 6.61] pg/mL, P=0.0003 and 4.98 [0.6; 7.8] pg/mL, P<0.0001, respectively)." (PMID 23967342, 2013). "Highly elevated levels of cytokines primarily produced by macrophages and dendritic cells (IL-6, MCP-1, TNF-α, IL-10) in M. tuberculosis-PbNK65 co-infected animals indicate that immune regulation is significantly impaired when malaria is concurrent with tuberculosis in mice." (PMID 23110184, 2012). "In controlled Plasmodium infections of malaria-naïve subjects, serum levels of pro-inflammatory cytokines, including TNF-α, IL-6, IFN-γ, and IL-12p40, increase at the time that parasites emerge from the liver and at the first appearance of parasitized erythrocytes." (PMID 22745697, 2012). "Monocytes produced high levels of IL-1β, IL-6 and TNF-α during acute malaria." (PMID 22745844, 2012). "We then showed for this rodent malaria model that the inhibitory effect observed in vivo was actually mediated by the IL-6 secreted by non-parenchymal liver cells in response to TNF-α stimulation." (PMID 21394207, 2011). "This study found increased plasma levels of proinflammatory cytokines: TNF‐α, IFN‐ɣ, IL‐1β, IL‐6, and GM‐CSF, and the anti‐inflammatory cytokine IL‐10 in malaria‐infected children than the controls without malaria, and the levels were higher in participants with high parasitemia." (PMID 39240033, 2024). "Notably, complement genes (C1QA, C1QB, C1QC), apoptotic genes (PDL1, PDL2, APOL1, APOL2, FAS), inflammatory caspases (CASP1, CASP5), TLR pathway genes (TLR1, TLR4, TLR5, TLR8), cytokines (IL6, IL10), and granzyme (GZMB) were among the genes upregulated during symptomatic malaria." (PMID 39161730, 2024). "However, the same study found higher levels of IL-6 in children with cerebral malaria than in children with noncerebral severe malaria, a finding replicated in a subsequent study in Malawi." (PMID 36801374, 2023). "•In malaria, the genetic analyses do not support therapeutic IL-6 inhibition." (PMID 36801374, 2023). "In conclusion, significantly increased levels of IL-6 were observed in patients with severe malaria compared with those in patients with non-severe malaria, indicating that IL-6 might be a candidate marker for severe malaria." (PMID 35396564, 2022). "The results based on the studies included in the meta-analysis indicated that IL-6 could be a marker for cerebral malaria as patients with severe malaria had higher mean IL-6 levels than those with non-severe malaria." (PMID 35396564, 2022). "Subgroup analysis of age groups showed higher mean IL-6 levels in those with severe malaria than in those with non-severe malaria among studies that enrolled patients of all age groups (P < 0.001, WMD = 133.57 pg/mL, 95% CI = 67.77−199.38 pg/mL, I2 = 95.6%, two studies)." (PMID 35396564, 2022). "Subgroup analysis of assays used to determine IL-6 levels showed a higher mean IL-6 level in cases with severe malaria than those with non-severe malaria among studies using an ELISA for IL-6 measurement (P = 0.006, WMD = 61.14 pg/mL, 95% CI = 17.46–104.81 pg/mL, I2 = 99.5%, nine studies)." (PMID 35396564, 2022). "Since a blockade of PD‐1/PD‐L1 signaling could not restore anti‐malaria immunity, we reasoned that late IL‐6 may regulate other immune‐cell populations." (PMID 35635376, 2022).
malaria (continued). "Results of the meta-analysis showed that patients with severe malaria had higher mean IL-6 levels than those with non-severe malaria [P = 0.04, weight mean difference (WMD) = 96.63 pg/mL, 95% confidence interval (CI) = 0.88 − 19.38 pg/mL, I2 = 99.9%, 13 studies]." (PMID 35396564, 2022). "Malaria studies in mice models have shown that CD4 + T cell intrinsic Bcl6 signalling is required for induction of Tfh responses, and that the cytokines IL-6 and IL-21 are also required whereas the presence of Type 1 IFN tended to compromise Tfh cells and Tfh-mediated GC responses." (PMID 34666102, 2021). "However, monocytes and macrophages do not produce typical inflammatory cytokines such as IL-6, IL-12, and TNFα during the earliest stages of malaria because of phagosomal acidification, whereas dendritic cells can." (PMID 31662766, 2019). "In addition to producing type I IFNs, DCs produce a wide range of pro-inflammatory cytokines, including TNF-α, IL-12, and IL-6, and chemokines, such as CXCL1, CXCL2, CCL2, CCL5, CXCL9, and CXCL10 in response to malaria parasites, and play crucial roles in malaria immunity and pathogenesis." (PMID 30619355, 2018). "Although P. vivax and P. falciparum malaria patients have similar cytokine profiles during infection, P. falciparum patients presented higher levels of IFN‐γ and TNF‐α, in acute phase and of IFN‐γ, IL‐6, IL‐8, IL‐17, and G‐CSF in convalescent phase than P. vivax patients." (PMID 29314720, 2018). "IL-6 and IL-10 levels were found to correlate positively with acute malaria in children infected with S. haematobium who developed P. falciparum malaria when compared with Schistosoma-negative children who developed malaria." (PMID 29970128, 2018). "We report high plasma levels of proinflammatory cytokines and chemokines (IFNγ, TNF, IL-6, CCL2, CCL3, CCL4, CXCL10) in severe malaria patients compared to baseline uninfected follow-up, which matched that of Py infection in mice in which we could conduct a temporal analysis." (PMID 27792766, 2016). "Severe malaria patients exhibit high levels of serum pro-inflammatory cytokines (TNF, IL-1β, IL-6, IL-8, IL-12, IFNγ) and chemokines (CCL2, CCL5, CXCL9, CXCL10), and lower levels of regulatory cytokines (IL-10, TGFβ, PGE2) compared to those with mild and asymptomatic malaria." (PMID 27792766, 2016). "A recent RNA-seq study of naïve and malaria-experienced Colombian volunteers who underwent CHMI with P. vivax also found no differential response in the fever-inducing inflammatory cytokines IL-1β, IL-6, IL-8 and TNF between naïve and malaria-experienced individuals at the time of diagnosis." (PMID 27506615, 2016). "Hepcidin was positively correlated with IL-6 (r = 0.4339; p = 0.0015), IL-10 (r = 0.5154; p = 0.0002), and parasitaemia (r = 0.3032; p = 0.0096) and negatively correlated with IFN-γ/IL-10 (r = −0.4369; p = 0.0017) and (TNF + IFN-γ)/IL-10 (r = −0.3776; p = 0.0075) in the mild malaria group." (PMID 26466783, 2015). "Interestingly, although no relations were observed between the number of malaria episodes and the levels of IL-6 and IL-10, patients with higher parasitemia produced higher levels of both cytokines." (PMID 24741587, 2014). "The negative correlation between age and both sCD163 and IL-6 levels seen in this study could thus be explained by the fact that people in Africa develop acquired immunity after repeated exposure to the malaria parasites." (PMID 24274254, 2013). "The fact that IL-6 increased upon infection in Dogon but not in Fulani, might imply this cytokine to be important in the pathogenesis of malaria." (PMID 22480186, 2012). "Despite the fact that neutrophils are an important source of cytokines, we found that except for IL-8 (CXCL8), the neutrophils from malaria patients produced none or very small amounts of pro-inflammatory cytokines (i.e., IL-1β, IL-6, and TNF-αin response to TLR agonists." (PMID 22745844, 2012).